CASP1 (caspase 1)
Diseases named in the same sentence as CASP1 in open-access papers (continued):
Sharing a sentence is not in itself a finding about the gene and the disease.
infection (continued). "Confirming what we observed during infection with B. pseudomallei, production of IL-1β following infection with B. thailandensis was dependent on NLRP3, ASC, and caspase-1 while pyropotosis was dependent on NLRC4." (PMID 25166912, 2014). "In epithelial cells, which are the primary sites of infection by C. trachomatis, as well as in human monocytes and dendritic cells, NLRP3 and ASC mediate inflammasome-dependent activation of caspase-1 and secretion of cytokines in response to C. trachomatis." (PMID 24324933, 2013). "Upon infection by intracellular bacteria or viruses, infected cells form an ASC pyroptosome, which rapidly recruits and activates caspase-1 resulting in pyroptosis and the release of the intracellular proinflammatory cytokines." (PMID 22723924, 2012). "We observed caspase 1 and caspase 3 cleavage and also PARP cleavage (data not shown) in a concentration-dependent manner after ATI-like and ATII cell infection with PR8 virus at 24 hpi and 48 hpi." (PMID 22672594, 2012). "Infection of macrophages with Y. pestis KIM5 under low MOI and short contact time (20 min) results in delayed caspase-1 activation, high level of IL-1β release and cytotoxicity in a YopJ dependent manner." (PMID 22563435, 2012). "The treatment with the inhibitors only during the first two days of infection significantly improved the survival in a similar manner as for the P2X7R and caspase-1-KO mice." (PMID 22558229, 2012). "To identify the NLR involved in IL-1β secretion, we infected bone marrow-derived wild type (wt) and knockout macrophages in NLRC4, NLRP3, ASC and Caspase-1 (all from C57BL/6 mice background) at MOI of 50 and quantified the IL-1β produced 24 h post-infection." (PMID 22848580, 2012). "At 12 h post infection, the cell lysate was subjected to SDS-PAGE and Western blotting with anti-caspase-1 p10 subunit specific antibody." (PMID 22295065, 2012). "However, infection of caspase-1-deficient mice revealed that increased host resistance to a Y. pseudotuberculosis YopP-expressing strain endowed with enhanced cytotoxicity does not require caspase-1." (PMID 22563435, 2012). "This is in contrast to the components required to respond to PA103 infection, which is dependent on NLRC4 and ASC as well as caspase-1." (PMID 20955240, 2011). "At 8 hours and, more so, at 24 hours post-infection, cultured BMDM infected with CP secreted IL-1β in a Casp1-dependent manner." (PMID 21731762, 2011). "In addition, during infection with Yp-YopJCO92 orYp-YopJC172A, higher amounts of IL-1β were secreted fromIkkβΔ BMDMs as compared toIkkβF/F macrophages, consistent with the idea that theNF-κB pathway negatively regulates processing and secretion of IL-1β viacontrol of caspase-1 activation." (PMID 21533069, 2011). "Various caspases, including the subfamily of inflammatory mediator (CASP1, CASP4), the apoptotic activator (CASP2, CASP8) and the apoptotic executioner (CASP7) were up-regulated in response to infection." (PMID 21110886, 2010). "Of note, infection with wild type M. marinum induced higher levels of pro-caspase-1 than ΔRD1, independent of the inflammasome, which might be explained by secretion of Esat-6, a major Esx-1 substrate that has been proposed to induce caspase-1 gene expression in macrophages." (PMID 20463815, 2010). "Treatment of THP-1 cells with caspase-1 inhibitor, zVAD-fmk, alone caused no induction of IL-1β but when combined with the infection with vMyxM013-KO virus resulted in the dramatic inhibition of IL-1β secretion at early time points, starting in the first hour post-infection." (PMID 19851467, 2009). "The contribution of caspase-1 and NALP/NAIP in host–pathogen interaction has been analyzed in vivo by using animal models of infection or in vitro by using cytokine and viability assays with monocytes/macrophages." (PMID 18166077, 2007). "However, ΔeseB-D, ΔeseB, ΔeseC, and ΔeseD were unable to induce host cell death, IL-1β release, Casp1 activation, or GSDMD cleavage following infection." (PMID 39951384, 2025).
infection (continued). "However, the induction of effector molecules involved in inflammasome activation, including CASP1 and GSDMD, occurs later in the infection, coinciding with high levels of DENV-2 replication." (PMID 40934228, 2025). "Additionally, as a downstream product of the NLRP3 inflammasome activation pathway, caspase-1 was evaluated, and accumulation of this protein was observed in the DENV-infected cells 24 and 36 h post-infection." (PMID 41471247, 2025). "We determined the neutrophil number in BALF at an earlier infection stage (4 hours after infection) and found no significant increase in the total cell count or neutrophil count in the Casp1-/- mice." (PMID 40359428, 2025). "In this study, we found that in the infection model of THP-1 derived human macrophages, which express multiple inflammasomes, E. tarda induced pyroptosis in a manner that depended on NLRC4, NLRP3, ASC, Casp1, and Casp4." (PMID 39951384, 2025). "RS218 infection triggered robust pyroptotic responses, including increased expression of IL-1β and GSDMD, enhanced GSDMD cleavage to its active N-terminal form, activation of caspase-1 and its cleavage into the p20 subunit, and elevated IL-1β secretion." (PMID 40821830, 2025). "First, we detect the expression of caspase 1 and caspase 11 in the liver of lethally (E. japonica) and non-lethally (E. muris) infected mice during the course of infection." (PMID 40488533, 2025). "We found here that in a macrophage infection model with the RIPK1-activating pathogen, Y. pseudotuberculosis, the cell death is RIPK1 driven, yet TBK1/IKKε inhibition also sensitizes cells to enhance secondary NLRP3-dependent caspase-1 activation." (PMID 40053580, 2025). "Additionally, despite robust infection establishment in the presence of both pan-caspase (z-VAD) and caspase-1 (VX-765) inhibitors, IL-1β production was attenuated in THP1/PMA/NLRP1 macrophages compared to DMSO-treated infection control." (PMID 40920844, 2025). "At 1 hr post-infection (hpi), we did not observe any significant differences in bacterial uptake between Pam3CSK4-primed WT and CASP1-/- THP-1 cells." (PMID 40162563, 2025). "The caspase-1 dependent pyroptosis pathway, specifically the ASC/NLRP3/caspase-1 axis, serves as a key mechanism promoting lytic cell death in RSV-infected macrophages, while infection-generated ROS positively regulate this lytic cell death." (PMID 41394101, 2025). "In the present study, we found that intestinal NLRP3 expression was significantly upregulated after infection in wild-type mice, whereas TRIM67 deletion inhibited this process, resulting in reduced caspase-1 activity and decreased pro-inflammatory cytokine release." (PMID 40572155, 2025). "In the present study, we found that infection with GoAstV activated the NLRP3 pathway, and the mRNA expression levels of NLRP3, cleaved caspase-1 and IL-1β were significantly upregulated in the infection group at 24 hpi and 48 hpi compared to those in the control group." (PMID 39502173, 2024). "Upon infection, macrophages expressed FLT4/VEGFR-3 and its ligand VEGF-C, and this signaling was involved in the inhibition of CASP1 (caspase 1)-dependent inflammasome activation and pyroptosis; it also enhanced MAP1LC3/LC3 activation for bacterial elimination." (PMID 38464522, 2024). "Dampening of pyroptosis via reduction of macrophage transcriptional activities was demonstrated upon L. donovani infection; transcriptional reduction of caspase-1, NLRP3, and other inflammasome-related genes was observed in PBMCs from VL patients and in macrophage-infection in vitro." (PMID 39392429, 2024). "Unlike the Casp1/11−/− mice however, Nlrp6−/− mice phenocopied their WT littermates in terms of infection-induced cecal pathology, with both groups displaying severely disrupted epithelial integrity, IEC sloughing and immune cell infiltration." (PMID 39428744, 2024). "Caspase-1, caspase-4, and caspase-11 cleave the GSDMD in response to infection." (PMID 38429762, 2024).
infection (continued). "Using this approach, we report that caspase-1 is required for optimal parasite control, promoting CD4+ T cell IFN-γ production and enhancing neutrophil and monocyte recruitment to the initial site of infection." (PMID 39446964, 2024). "Upon high-MOI infection with WT MCMV, the fully processed Caspase-1 p20 fragment was detected." (PMID 38278864, 2024). "While Fut2 transcription was significantly increased (~10-fold) in the ceca of infected WT mice compared to baseline, it was not induced upon infection of Casp1/11−/− mice." (PMID 39428744, 2024). "Also, for IL-18 and caspase-1, there is a statistically significant reduction comparing WT THP-1 and KO THP-1 cells after infection with Lt-P10." (PMID 38707903, 2024). "Accordingly, infection or cellular stressors can lead to cell death by the combinatory crosstalk of pyroptotic, apoptotic, and necroptotic molecules (like ZBP1, RIPK1, RIPK3, CASP1, CASP8, and NLRP3, MLKL, and GSMDs) to effectively control pathogenic invasion." (PMID 38590437, 2024). "We next sought to determine how Casp1−/−, Casp11−/−, Nlrp3−/− and Asc−/− mice were protected against the infection, whereas Casp1/11−/− was not." (PMID 39533032, 2024). "Toxoplasma gondii has been shown to promote inflammasome formation, but the cell types utilizing caspase-1 and the downstream effects on immunological outcomes during acute in vivo infection have not been explored." (PMID 39446964, 2024). "Furthermore, components of the NLRP3 inflammasome activation pathway, including NLRP3 itself, caspase-1, caspase-1 p20, and ASC, were all elevated at the protein level 12 h post-infection." (PMID 37594276, 2023). "Because inflammasome activation of caspase 1 can lead to pyroptotic cell death, we assessed the release of LDH from WT MeV and LAMV-infected THP-1 cells 24 h after infection to determine whether MeV activation of the inflammasome resulted in rapid cell death." (PMID 36851476, 2023). "In contrast, caspase-1 inhibition blunted the amplitude of the HIV-1 induced cytokine storm as VX-765 treated huNSG mice only upregulated significantly the levels of IP-10 and TNF-α after infection (p<0.05 and 0.05, respectively)." (PMID 36800238, 2023). "Similarly, Casp1/11+/–Casp8–/–Ripk3–/– mice retain the ability to recruit Caspase-1 to NLRC4 and to initiate cell death via Caspase-11 and should also thus be resistant to infection." (PMID 36645406, 2023). "RT-qPCR did not reveal significant differences in the amount of TMEV RNA as well as Ifnb1, Isg15, Eif2ak1 (PKR), Tnfa, Il1a, Il1b, Il6, Il10, Il12 (p40) and Ifng transcript numbers in the brain of Asc−/− and Casp1−/− mice and their respective wild type littermates at 4 days after TMEV infection." (PMID 37414913, 2023). "Casp1/11–/–Casp8+/–Ripk3–/– mice retain Caspase-8 function downstream of both NLRC4 and TNFα and based on our previous experiments with Casp1/11–/– mice, we expected that these mice would be resistant to infection." (PMID 36645406, 2023). "Additionally, mRNA levels of pyroptosis-related genes (NLRP3, ASC, caspase-1, GSDMD, IL-18, and IL-1β) in the kidneys with W24Δhcp1 infection are considerably lower than in those with WT W24 infection." (PMID 36977062, 2023). "By microscopy, no cell lysis nor activation of inflammasome caspase-1 was observed under these infection conditions, though was increased at a higher multiplicity of infection (MOI)." (PMID 37068092, 2023). "A similar case occurred during an infection of CRIB cells with BoHV-1, which tested the activations of IFI16 and NLRP3 upstream of caspase 1 and found a decrease in the viral titer of cells treated with glyburide, which inhibits the indirect action of the inflammasome." (PMID 37515181, 2023). "In an earlier report, we showed that PAO1 infection of peritoneal neutrophils induced release of IL-1β that was attenuated (~50-60%) but not completely suppressed in neutrophils from caspase-1-/- and Nlrc4-/- mice." (PMID 37730693, 2023).
infection (continued). "Next, we found no significant change in caspase-1 activation following infection in A549 cells with WT ZIKV or ZIKV DB-1 mutants." (PMID 37417764, 2023). "A549s treated with caspase 3 inhibitors underwent less cell death after 36 hours of infection; this was not seen with caspase 1 inhibitors." (PMID 37974615, 2023). "Besides, monocytes infection activates AIM2 inflammasome, caspase-1 and GSDMD cleavage, and the expression level of GSDMD on the cell membrane and cytoplasm of monocytes is linked with the severity of infection." (PMID 37063905, 2023). "The data obtained show that M. furfur activates the inflammasome by inducing the expression of Il-1β, Caspase-1, IL-18, and NLRP-3 after 4 h of infection, while the simultaneous addition of L. plantarum totally inhibits this activation, bringing them back to the control values." (PMID 38132754, 2023). "Infection with live AC047 also resulted in caspase-1 cleavage and IL-1ß release, an effect not seen in the T3SS-deficient mutant." (PMID 37598340, 2023). "RAW264.7 cells with and without pretreatment by caspase-1 inhibitor were infected with E. faecalis OG1RF at multiplicities of infection (MOIs)." (PMID 36294525, 2022). "STEC O113 ΔsubAB infection clearly enhanced formation of the NLRP3/pro-caspase-1 assembly but SubABwt treatment did not." (PMID 35345462, 2022). "Furthermore, genetic deletion of CB2R amplified the NLRP3 activation post-PA infection, besides the observation of higher levels of NLRP3, ASC, and caspase-1(p20) levels in the lungs of CB2KO mice." (PMID 36463179, 2022). "Another study reported that upon infection of intestinal epithelial cells with RV, the viral RNA helicase Dhx9, and inflammasome Nlrp9b recognized short stretches of dsRNA thus forming inflammasome complexes with the adaptor proteins such as ASC and caspase-1." (PMID 35806033, 2022). "Among the different tested neutrophil genotypes, significant resistance to pyroptotic cell lysis (LDH release) was only observed in Casp1-/-, Casp1-/-Casp11-/-, Nlrc4-/- and ASC-/- BMNs upon infection with P. aeruginosa pyroptotic strains PAO1ΔExoS and PP34ΔExoU." (PMID 35849616, 2022). "In addition, quantitative real-time PCR assay of EV71 replication was applied in WT/KD cells at different times after infection, results confirmed that both NLRP3/Caspase-1 and cellular EV71 replications increased rapidly with the increment of exposure time." (PMID 35807435, 2022). "Furthermore, ECHO 11 infection triggered NLRP3 inflammasome activation, as evidenced by cleavages of GSDMD, pro-IL-1β and pro-caspase-1, and the release of LDH." (PMID 36026486, 2022). "Moreover, treatment with caspase-1 specific inhibitor YVAD restored the PI+ cell fraction and LDH release that promoted by TREM knockout in BMDMs after infection." (PMID 36068223, 2022). "When microglial cells face a pathogen, for instance Streptococcus pneumoniae, a microorganism whose infections produce meningitis, they respond by assembling inflammasome NLRP3, activating caspase-1, secreting IL-1β and IL-18 and inducing cell death by pyroptosis." (PMID 35783102, 2022). "The active end of caspase-1 and gasdermin D (GSDMD) were highly expressed even after infection." (PMID 35761358, 2022). "Additional hallmark pyroptotic processes, such as the cleavage and release of Caspase-1 and GSDMD, were apparent upon infection of BMDMs with the Δvprh/Δhns1 strain; however, they were undetected upon inactivation of T6SS3 or upon the addition of inflammasome inhibitors." (PMID 36155655, 2022). "To address whether Casp-1 is involved in SVA-induced IL-1β production, we assessed IL-1β secretion and IL-1β maturation form expression in BMDM cells after SVA infection." (PMID 35254168, 2022).
infection (continued). "By using microglia-derived cell lines, researchers observed that HIV promotes the synthesis of pro-IL-1β after 4 h post-infection and the release of this cytokine after 24 h; in agreement, brains of patients with AIDS showed high levels of IL-1β, IL-18 and caspase-1." (PMID 35783102, 2022). "Post-infection, complexes of IFI16, ASC, and caspase 1 were identified by co-immunoprecipitation." (PMID 35458396, 2022). "Infection of intestinal epithelial cells with transmissible gastroenteritis virus (TGEV), a type of coronavirus, led to the production of pro-IL-1β, its processing and maturation via activation of caspase-1." (PMID 35806033, 2022). "Furthermore, we confirmed that infection of human blood neutrophils with two different Pseudomonas aeruginosa strains (PAO1 and CHA) also triggered a Caspase-1-dependent, yet Caspase-4/5, -3/7 and -8-independent, IL-1ß release and neutrophil lysis." (PMID 35849616, 2022). "NLRP3 and caspase-1 protein expression in the LPS + ATP group and the HPI groups increased gradually with time post-infection, which is similar to the pattern of increased caspase-1 protein content in human monocyte macrophages following Helicobacter pylori infection." (PMID 33678162, 2021). "Compared to TLR1/2 signaling and pyruvate catabolic pathways, caspase-1-induced pyroptosis did not play a major role in our infection model." (PMID 34933448, 2021). "Consistent with the lack of a significant difference in the infection phenotype between the WT and Caspase-1/11−/− mice, the levels of the chemokine Cxcl1 were also comparable." (PMID 34011393, 2021). "IAV–ΔNS1 infection, however, did not lead to CASP1 activation in WT BMDMs, suggesting that the lack of NS1 protein in IAV abolished activation of the NLRP3 inflammasome." (PMID 33766561, 2021). "While RhoA-GTP was absent in WT BMDMs upon infection, it was present in Aim2–/–, Asc–/– and Casp1–/– BMDMs." (PMID 34471287, 2021). "Evidence in murine models indicates that the early recognition of S. Typhimurium infection (<36 h post-infection) generates the activation of NAIP 1–6 proteins, NLRC4 inflammasome, and caspase-1, which restrict this replicative niche due to the expulsion of the infected IECs from the mucosa." (PMID 34276584, 2021). "Similarly, we found upregulated expressions of cleaved caspase-3, pMLKL, cleaved caspase-1, and GSDMD-N proteins in the three E. faecalis infection groups at 6 and 12 h post-infection, compared to the protein expression levels in the control group (P < 0.05)." (PMID 34513732, 2021). "At 24 h post-infection with J2315, WT BMDMs showed pronounced cleavage of both Caspase-1 and Gasdermin-D, which was either absent or reduced in Casp1/11-/- and Ifnar1-/- BMDM, respectively." (PMID 33684179, 2021). "Activation of caspase-1 was detectable in WT THP-1 cells but not in THP-1-defCASP1 cells following infection with PA14 and PAO1." (PMID 33664232, 2021). "Similar to the phenotype observed in Casp8/Ripk3/Casp1/11−/− mice, B. thailandensisvgrG5ΔCTD infection was also attenuated in mice lacking caspase-1/11 or GSDMD." (PMID 34154417, 2021). "Caspase-1−/− and Asc−/− BMDMs in contrast showed significantly reduced IL-1β levels upon infection, indicating that NLRP3 inflammasome components (ASC) and targets (caspase-1) function upstream of GSDMD and have a potential dual role in cell death and release of pro-inflammatory cytokines." (PMID 34718331, 2021). "Casp1/11 double knockout BMDMs failed to secrete IL-1β and undergo cell death during ΔpknF mutant infection in contrast to infection of wild-type BMDMs with ΔpknF mutant." (PMID 34324582, 2021). "Infection assays in polarized human colonic epithelial cells (C2Bbe1) have shown that the caspase-4 but not caspase-1 is required for inflammasome activation and subsequent secretion of IL-18 in an LPS-dependent manner." (PMID 34276584, 2021).